DLL4 (delta like canonical Notch ligand 4)
Diseases named in the same sentence as DLL4 in open-access papers (continued):
Sharing a sentence is not in itself a finding about the gene and the disease.
muscular dystrophy (1 paper, 2016). Muscular dystrophy (MD) refers to a group of more than 30 genetic diseases characterized by progressive weakness and degeneration of the skeletal muscles that control movement. "Therefore, we hypothesize that MCK-N1ICD upregulates Dll4/Jag2 in myofibers, which in turn activates Notch signaling in juxtaposed SCs to regulate their self-renewal in response to aging and muscular dystrophy." (PMID 27644105, 2016).
osteoporosis (1 paper, 2022). A condition of reduced bone mass, with decreased cortical thickness and a decrease in the number and size of the trabeculae of cancellous bone (but normal chemical composition), resulting in increased fracture incidence. "We propose that Dll4(E12) might serve as a promising example for the design of future anti-osteoporosis drugs." (PMID 35119364, 2022).
osteosarcoma (1 paper, 2025). A usually aggressive malignant bone-forming mesenchymal neoplasm, predominantly affecting adolescents and young adults. "This conflicts with a report that wt Dll4 cis-inhibited Notch2 in U2OS osteosarcoma cells." (PMID 39751380, 2025).
periodontitis (1 paper, 2021). An acute or chronic inflammatory process that affects the tissues that surround and support the teeth. "Therefore, Dll-4 may present a promising therapeutic target for immunomodulation in the development of periodontitis and deserves further exploration in vivo." (PMID 33981487, 2021).
peripheral arterial disease (1 paper, 2021). A disorder of the arteries supplying the upper and lower extremity and the visceral organs. "Recent studies in unstable atherosclerotic plaque from patients with peripheral arterial disease identified highly expressed Notch ligand Delta-like 4 (Dll4) and miR-424-5p, complex associated with disease progression." (PMID 33985567, 2021).
postmenopausal osteoporosis (1 paper, 2022). Metabolic disorder associated with fractures of the femoral neck, vertebrae, and distal forearm. "Next, we investigated whether Dll4(E12) treatment provides any beneficial effects in the ovariectomy model of postmenopausal osteoporosis." (PMID 35119364, 2022).
rectal cancer (1 paper, 2023). A primary or metastatic malignant neoplasm that affects the rectum. "SELENBP1 can bind to Delta-like ligand 4 (DLL4) and antagonize the DLL4/Notch1 signaling pathway, inhibiting rectal cancer angiogenesis." (PMID 36770890, 2023).
retinoblastoma (1 paper, 2016). A malignant tumor that originates in the nuclear layer of the retina. "Two shRNA contructs, TRCN0000033415 (n.1) and TRCN0000033418 (n.2), reduced by more than 70% the mRNA levels of DLL4 in both retinoblastoma lines, as compared to scrambled shRNA." (PMID 27661116, 2016). "Among the DLL ligands, DLL4 mRNA appeared to be highly expressed in both retinoblastoma lines, compared to DLL1 and DLL3, and it was also highly expressed in the non-neoplastic adult retina." (PMID 27661116, 2016). "Notch pathway components were present in WERI Rb1 and Y79 retinoblastoma lines, with Jag2 and DLL4 more highly expressed than other ligands, and Notch1 and Notch2 more abundant than Notch3." (PMID 27661116, 2016).
thymoma (1 paper, 2021). A neoplasm arising from the epithelial cells of the thymus. "Stimulation of the thymoma cell line EL4 with Notch ligand Delta-like 4 (DLL4) induced expression of the genes involved in ERAD including Sel1l, Hrd1, Os9, and Edem1 as well as SEL1L proteins." (PMID 34240701, 2021).
thyroid cancer (1 paper, 2019). "Moreover, TF AHR could positively regulate target gene DLL4 to cause the migration and angiogenesis of thyroid cancer cells." (PMID 31126066, 2019).
vascular malformation (1 paper, 2013). A non-neoplastic disorder that is the result of defects of vascular morphogenesis. "Delta-like 4 (Dll4), a transmembrane ligand for Notch receptors, has emerged as the critical ligand in Notch signalling-mediated vascular malformations in mice." (PMID 24373503, 2013).
vasculitis (1 paper, 2021). "Firstly, the level of DLL4 is also increased in many other diseases, such as infections by various pathogens, cardiovascular disease, kidney disease, tumors, and vasculitis." (PMID 34362349, 2021).
viral infection (1 paper, 2009). "siRNA knock-down of ERK1 and ERK2 significantly reduced KSHV-induced DLL4 expression in LEC suggesting a role for this pathway in the upregulation of DLL4 during viral infection." (PMID 19816565, 2009). "Upregulation of JAG1 and DLL4 by KSHV could therefore alter the expression of cell cycle components in neighbouring uninfected cells during latent and lytic phases of viral infection, influencing cellular quiescence and plasticity." (PMID 19816565, 2009).
tumor (321 papers, 2008 to 2026). "We hypothized that DLL4 is directly associated to Notch2 and/or Notch3 receptors resulting in Notch downstream activation and increased tumor cell proliferation." (PMID 39951484, 2025). "The Notch signaling pathway, including DLL4-Notch4 interactions, has been associated with vasculogenic mimicry, tumor recurrence, and prognosis in NSCLC and other malignancies." (PMID 38612588, 2024). "DLL4 signaling is often associated with regulation of tumor angiogenesis, but also serves cancer cell-autonomous roles in tumor growth and metastasis." (PMID 37993804, 2023). "Blockage of the VEGF signaling pathway causes a rapid and marked decrease in the expression of Dll4 by tumor vessels." (PMID 36910471, 2023). "Lewis Lung Carcinoma (LLC) cells were used to study tumor metastasis in vivo, by endothelial-specific Dll4 loss-of-function." (PMID 35406423, 2022). "In contrast, Jag1 deletion induces the ectopic expression of Dll4 in hepatocytes along with the loss of Notch2 signaling, leading to the tumor progression." (PMID 35064244, 2022). "Important signaling pathways such as VEGF/VEGFR and Notch/Dll4 (Delta-like ligand 4) are implicated in tumor angiogenesis." (PMID 34869355, 2021). "Alternatively, ectopic expression of NOTCH3 in ECs was associated with both increased DLL4 expression and increased tumor angiogenesis in a murine xenograft model." (PMID 34043714, 2021). "In other words, JAG1 and DLL4, as Notch1 ligands, together cause normal angiogenesis, and any dysfunction of either causes inefficient angiogenesis and invasive tumor." (PMID 36643842, 2021). "DLL-4 is critically important in vascular development, and in the context of cancer, its upregulation has been demonstrated in both tumour cells and associated tumour blood vessels." (PMID 32575680, 2020). "In relevant in vitro and in vivo cancer models, DLL4 has also been implicated in chemoresistance, tumour angiogenesis and CSC activity." (PMID 30975104, 2019). "The inhibition of DLL4/Notch signalling causes large vessels and increases vascular density in tumours." (PMID 31429823, 2019). "It was demonstrated that Dll4 haploinsufficiency causes embryonic lethality and reduces tumor growth due to defects in the development of the vasculature." (PMID 30691003, 2019). "In T-ALL cells, where mutations in NOTCH1 are frequent and well characterized, DLL4 plays an important role as part of the tumor microenvironment contributing to early steps of T-ALL cell growth." (PMID 31676012, 2019). "The positive rate of DLL4 expression was significantly associated with tumor grade, tumor size, LNM, DM, and TNM stage." (PMID 30593175, 2018). "The humanized anti-Dll4 mAb OMP21M18 caused inhibition of tumor growth in PDX models and is currently being tested in several clinical trials, either as a single agent or in combination with other drugs." (PMID 29462871, 2018). "Overall, studies on the association between tumor metastasis and prognosis suggest that VM, Notch4, DLL4, and KAI1/CD82 affect cancer progression." (PMID 30593175, 2018). "And silencing Dll4 in tumor cells results in inhibition of tumor growth, consistently, silencing Dll4 in mouse tumor-associated endothelial cells significantly inhibits angiogenesis." (PMID 28284219, 2017). "In all three models, remarkable tumor burden reduction due to Dll4 overexpression was consistently associated with decreased endothelial density and presumably reduced overall tumor blood supply." (PMID 28288569, 2017). "This prompted us to investigate the breakpoint region of the translocation, which uncovered a gene that encodes a Notch ligand, DLL4, (locus at 15q15.1), a key target in tumor vasculature." (PMID 27542210, 2016). "Radiation combined with Dll4 mAb also caused significant cell death 7 days following therapy, however tumour volumes in this condition were noted to be larger than tumour treated with the triple combination therapy." (PMID 24736631, 2014).
tumor (continued). "Specially, the risk of hematogenous metastasis in tumor expressed high-level of DLL4 density was 23.4 fold of that in tumor expressed low-level of DLL4 density." (PMID 24931473, 2014). "The Dll4-Notch signaling pathway has been implicated in regulating tumor initiating cells, also referred as cancer stem cells (CSCs)." (PMID 25393540, 2014). "Multivariate logistic analysis of RCC specimens showed that tumor hematogenous metastasis not only depended on angiogenesis but was also associated with tumor size and DLL4 density." (PMID 24931473, 2014). "Down-regulated miR-30a in ccRCC was associated with tumor hematogenous metastasis through increasing microvessel density by targeting angiogenesis-specific DLL4." (PMID 23826258, 2013). "Sprouting angiogenesis is a hallmark of tumor neovascularization, and Dll4/Notch1 signaling functions to inhibit vessel sprouting." (PMID 23601498, 2013). "Histological analysis of tumors treated with DLL4/NOTCH1 inhibitors has revealed that the reduced tumor growth is associated with an apparent increase in tumor vascular density." (PMID 21824400, 2011). "Greater efficacy was observed when sEphB4-Alb was combined with either Dll4 allele deletion or sDll4 in regards to tumor size, vessel perfusion and mural cell recruitment." (PMID 21092311, 2010). "Dll4 allele deletion or soluble Dll4 treatment resulted in increased tumor vessel density, reduced mural cell recruitment and vessel perfusion which resulted in reduced tumor size." (PMID 21092311, 2010). "A number of recent reports indicate that this is also the case during tumour neoangiogenesis, with loss of Notch activation by Dll4 resulting in an inefficient vascular bed due to a disproportionate increase in vessel branching." (PMID 19087347, 2008). "Similar associations between VEGF signalling, growing vessels and Dll4 expression have been found in tumour vessels." (PMID 18827808, 2008). "Additionally, both the JAG1 and DLL4 levels were associated with poor differentiation, invasion, regional lymph node metastasis, a maximum tumor size > 5 cm, TNM III/IV disease, and survival." (PMID 35673567, 2022). "Dll4 overexpression has proven to be implicated in cancer development by promoting tumor growth." (PMID 35406423, 2022). "Targeted therapies against Dll4 may be particularly interesting from a tumour vasculature perspective, as blockade of Dll4 causes hypersprouting in the vasculature by altering the tip/stalk cell balance, which leads to a poorer blood supply for the tumours." (PMID 35472289, 2022). "It has been implicated that the Dll4-Notch signaling pathway regulates tumor-initiating cells, i.e., cancer stem cells, which has been reported to be characterized by self-renewal, tumor initiation, and differentiation." (PMID 35945960, 2022). "According to in vitro experiments of human ACC cell line, SW13 cells, overexpression of ESM1 upregulated CDK1 and p21-mediated G2/M-phase transition, cell proliferation, cell migration, cell invasion, and accumulation of tumor mutation burden (TMB) via DLL4-Notch signaling pathway." (PMID 34858850, 2021). "Furthermore, endothelial-specific loss of DLL-4 resulted in tumour vessel regression along with a reduction in both EMT and cancer stem cells (CSCs)." (PMID 32575680, 2020). "Studies with pharmacological compounds or with classical knockout or conditional mouse lines revealed that loss-of-function (LOF) of Dll4, Notch1 or Rbpj results in severe vascular developmental defects and a marked delay in tumour growth due to an abnormal increase in angiogenesis." (PMID 31043605, 2019). "Dll4/Notch signaling is also implicated in tumor angiogenesis." (PMID 31771184, 2019). "Blocking DLL4 signaling inhibits tumor growth, which may be associated with defective maturation of the tumor vascular network and poor tissue perfusion." (PMID 31739580, 2019).
tumor (continued). "Moreover, the contribution of endothelial Cdk5 to tumor angiogenesis and the underlying mechanism such as the Dll4/Notch driven angiogenic signaling are important subjects of this work." (PMID 26755662, 2016). "In contrast, co-localization analysis with the vascular endothelial marker, CD31, showed a significant reduction of Dll4 specifically on tumor vasculature caused by miR-27b mimic; in agreement, miR-27b inhibitor clearly augmented Dll4 expression by the tumor vasculature." (PMID 26161255, 2015). "Furthermore, Dll4 expression levels were found to be associated with tumor differentiation, invasion and metastasis." (PMID 25364440, 2014). "When DLL4 was silenced in vivo using nanoparticle delivery of a DLL4 specific siRNA to mice harboring A2780 or SKOV3ip1 cell line derived xenografts, the targeting of both tumor cells and tumor-associated mouse endothelial cells inhibited tumor growth and deregulated angiogenesis." (PMID 25366565, 2014). "Moreover, univariate and multivariate analyses showed that tumor hematogenous metastasis not only was depended on microvessel density but was also associated with tumor size and DLL4 density." (PMID 24931473, 2014). "However, recent reports have shown a strong association of DLL4 expression in the cellular membrane of tumor cells themselves." (PMID 23898884, 2013). "To test this hypothesis, we performed luciferase assays to determine whether miR-30a bound to the 3′-UTR of DLL4 and whether miR-30a expression was associated with tumor microvessel density (MVD) and hematogenous metastasis status." (PMID 23826258, 2013). "Dll4 is associated with tumor vessel maturation and remodeling." (PMID 23064377, 2013). "In addition, anti-Dll4 treatment revealed that the reduced tumor growth was associated with an apparent decrease in tumor vascular density." (PMID 23028940, 2012). "At present, however, the mechanism underlying DLL4-mediated tumor initiation and/or progression remains unclear." (PMID 21824400, 2011). "The association between Dll4 and tumor resistance to anti-VEGF inhibition suggests that targeting Notch factors in addition to VEGF may prove to be of greater therapeutic effect." (PMID 22087289, 2011). "Since inhibition of DLL4 leads to excessive branching of tumor vessels, the other plausible cause of inefficient blood flow could be the manifestation of a chaotic vascular network lacking a functional hierarchy." (PMID 21824400, 2011). "Specifically, the mechanisms underlying the reduced tumor vascular perfusion induced by Dll4-Notch inhibition remain unclear." (PMID 21923938, 2011). "A recent report demonstrated that chronic Dll4 blockade induced vascular proliferation in liver of mice, rats, and monkeys with associated hepatocellular changes, as well as the development of subcutaneous vascular lesions in rats, referred to as neoplasia." (PMID 21923938, 2011). "Overall, inhibition of Dll4/Notch causes reduced tumor growth." (PMID 21092311, 2010). "Consequently, mRNAs encoding VEGF-A, -C, -D, FGF-2, HIF1A or DLL4 that are expressed by tumour cells or microenvironment (such as DLL4 expressed by TIP cells which are furthest away from the circulating blood are still efficiently translated while cap-dependent initiation is compromised." (PMID 32111004, 2020). "Furthermore, DLL4 stimulation of NOTCH1-mutated Mino cells enhanced tumor cell migration and angiogenesis, which could be abolished by treatment with OMP-52M51." (PMID 31676012, 2019). "Basically, vascular defects self-repair and reperfusion over long-term Dll4/Notch-suppression may revert tumor growth, particularly in association with increasing malignant cell invasiveness, previously documented as a consequence of antiangiogenic-induced hypoxia." (PMID 28288569, 2017). "However, as these cells are implicated in tumor angiogenesis, it is conceivable that the effect of Dll4 on these cells may be a consequence of its angiogenic function." (PMID 28086833, 2017).